BCL2 (BCL2 apoptosis regulator)
Diseases named in the same sentence as BCL2 in open-access papers (continued):
Sharing a sentence is not in itself a finding about the gene and the disease.
cancer (continued). "The main problems with the application of Bcl-2 antagonists in cancer treatment are their poor water solubility and toxicity to normal cells." (PMID 37744063, 2023). "BCL-2 inhibition has been shown to increase the response of cancer cells to radiation as well as chemotherapeutic agents." (PMID 37976029, 2023). "The previously reported senescent cell eliminators ABT263 and ABT737 are BH3 mimetic inhibitors of anti-apoptotic proteins (Bcl-xL, Bcl-2, and Bcl-w) developed for cancer therapy." (PMID 36057013, 2023). "This, in turn, downregulates Bcl-2 protein expression, ultimately inducing apoptosis in cancer cells and demonstrating antitumor effects." (PMID 37860067, 2023). "In this study, PEI2k-conjugated HEC (HECP2k) was developed for anti-cancer drug, doxorubicin (Dox), and Bcl-2 siRNA co-delivery systems." (PMID 36840030, 2023). "Bcl-2 is an anti-apoptotic proteinthat is highly expressed in cancer cells and promotes their survival.The molecular docking study suggested that the newly synthesized moleculecould act as a Bcl-2 inhibitor." (PMID 36858050, 2023). "Treated with Ro5-3335, a RUNX1-CBFβ interaction inhibitor, the level of p-FOXO1Ser256 and Bcl-2 were significantly changed in control cancer cell lines (SKOV3, OVCAR3), meanwhile the expression level of FOXO1 was almost unchanged after Ro5-3335 treatment." (PMID 38057816, 2023). "Continued research and clinical trials can reveal the full potential of Bcl-2 inhibition in cancer treatment." (PMID 37834104, 2023). "Cancer progression mainly depends on the balanced levels of pro-apoptotic proteins, such as Bax, and anti-apoptotic proteins, including BCL2." (PMID 37728703, 2023). "Cell death escape represents a cancer hallmark, and B-cell/CLL lymphoma 2 (BCL-2) family proteins play a pivotal role in tumorigenesis and survival." (PMID 36835136, 2023). "In this respect, Antimycin A has been proposed as an inhibitor of the anti-apoptotic Bcl-2 proteins, but its use was limited due to the high concentrations required to block cancer cells growth in vivo." (PMID 37760033, 2023). "Both Bax and Bcl-2 as well as their ratio have been regarded as prognostic markers in various cancers." (PMID 36826047, 2023). "Lactobacillus plantarum DGK-17-fermented soybean seed extract can induce cancer cell apoptosis by regulating the protein expression of caspase 9, 3, BCl-2 and Bax, thereby inhibiting HCT-116 cell growth." (PMID 37570647, 2023). "Bax is a major proapoptotic member of the B-cell lymphoma 2 (Bcl-2) family proteins that control apoptosis in normal and cancer cells." (PMID 37370088, 2023). "The mechanism of action involves the selective inhibition of BCL-2 that is aberrantly expressed in the cancer cells, resulting in cell death by apoptosis." (PMID 37198212, 2023). "Anti-apoptotic BCL-2 proteins are commonly highly expressed in cancer and are readily targetable by a suite of BH3 mimetics." (PMID 37898609, 2023). "ABT-263 (Navitoclax), a BH3-mimetic targeting with high affinity Bcl-2, Bcl-w, Bcl-xL, displayed senolytic properties on normal senescent cells and this effect has recently been extended to cancer cells displaying senescent features." (PMID 36739330, 2023). "Bcl-2 overexpression and Bax underexpression can lower the sensitivity of cancers to chemotherapeutic drugs and avoid apoptosis." (PMID 36895009, 2023). "MDR-related cancer cells also reveal elevated levels of Bcl-2 and abnormal activation of the PI3K and AKT pathways." (PMID 38186578, 2023). "Previous studies show that fermentation induces apoptosis of cancer cells, mainly through the regulation of the expression of caspase 3, 7, 8, 9, BCl-2 and Bax." (PMID 37570647, 2023).
cancer (continued). "The influence of Ag/MgO nanoparticles on the expression of the Bcl-2 protein in cancer cells was less apparent." (PMID 37159701, 2023). "It produces MVs that have cytotoxic effects on cancer cells at certain concentrations and induce apoptosis in liver cancer cells, primarily by downregulating the expression of bcl-2 and bax genes in cancer cells." (PMID 37860067, 2023). "The use of ABT-263, a well-described senolytic compound targeting Bcl2 anti-apoptotic proteins, killed pancreatic gemcitabine-treated senescent-like cancer cells in vitro." (PMID 36739330, 2023). "Our study demonstrates the present status and future outlook of BCL-2 inhibitors for cancer therapy and attempts to find effective solutions for the barriers to their broad applicability." (PMID 37894324, 2023). "PAWR induces the switching from the autophagia to apoptosis selectively in cancer cells by down-regulating the antiapoptotic protein BCL2." (PMID 38069262, 2023). "For example, bromodomain and extra-terminal families (BETs) are epigenetic proteins redundant in many types of cancer cells and they regulate the transcription of oncogenes such as c-Myc and BCL-2." (PMID 36839734, 2023). "It is crucial to consider multiple factors, such as the heterogeneity and specific characteristics of the cancer type, the sample size, and potential confounding variables, when interpreting BCL2 expression." (PMID 38067251, 2023). "This review offers innovative perspectives for translational studies on the application of BCL-2 inhibitors in cancer therapy." (PMID 37894324, 2023). "The upregulation of antiapoptotic members, such as BCL2, occurs in various cancers, including ALL, leading to resistance to therapy-induced apoptosis." (PMID 37679323, 2023). "Apoptosis is crucial in preventing cancer development and is mediated by proteins such as BCL-2 and BAX, which leads to rapid cell death with unique biochemical and morphological characteristics." (PMID 37047788, 2023). "BH3 mimetics, including ABT-263, were originally developed as anticancer agents in response to the observation that some cancer cells overexpress BCL-2 and BCL-XL." (PMID 36752201, 2023). "In terms of biochemical mechanisms, NF-κB activation by the engagement of TLRs plays a pivotal role in cancer proliferation, survival, angiogenesis, and progression through the up-regulation of IL-6, Bcl-xL, Bcl-2, Bcl-xs, XIAP, and VEGF genes." (PMID 37287005, 2023). "The dysregulation of BCL2 expression has been reported in various cancers, with both up-regulation and down-regulation observed depending on the cancer type." (PMID 38067251, 2023). "Certain taccalonolides are effective towards the drug-sensitive and multidrug-resistant cancer cells through arresting the G2-M cell cycle, and inducing BCl-2 phosphorylation and cell apoptosis." (PMID 37444418, 2023). "They resensitize cancer cells through the downregulation of MCL-1 expression in the FLT3 mutated cells, resulting in the stronger efficacy of BCL-2 inhibitors." (PMID 37958832, 2023). "We found that DEGs in cancer-related signaling pathways, occurring in most pathways, are responsible for the stress response (GADD45), regulate apoptosis (BCL2), NF-κB subunits and other genes associated with immune response, apoptosis, and the cell cycle." (PMID 36982223, 2023). "BAX and Bcl‐2 genes were studied with qRT‐PCR to investigate the different ways that cancer cells undergo apoptosis." (PMID 37285457, 2023). "An earlier study found that administration of coumarin‐based benzopyranone derivatives (20 μM) up‐regulated the apoptotic pathway via Bax protein expression but down‐regulated Bcl‐2 protein expression in human lung (A549) cancer cells." (PMID 37697969, 2023).
cancer (continued). "MCL-1 specific inhibitors MIK665, AMG 176, AZD5991 have advanced to phase I/II clinical trials for cancer therapies, some in conjunction with the BCL-2 inhibitor ABT-199 (rev in:)." (PMID 37864894, 2023). "Cancer cells exhibiting DNA fragmentation, changes in expression of several apoptotic proteins such as Bcl2, cytochrome-c and formation of cleaved products of caspase 3 and PARP-1 suggests ellagic acid induces cell death via mitochondrial pathway of apoptosis." (PMID 37256897, 2023). "In cancer, there is an inhibition of apoptotic pathways through the up-regulation of anti-apoptotic proteins (Bcl-2) and the downregulation of the pro-apoptotic proteins (Bax), resulting in intrinsic resistance to chemotherapy." (PMID 37623253, 2023). "CM-EXOs administration resulted in a significant increase in Bax expression and a significant decrease in Bcl2 expression in cancer cells relative to the control cells." (PMID 36851428, 2023). "The relationship between BCL2 gene expression and cancer is complex and can vary depending on the specific cancer type and context." (PMID 38067251, 2023). "When BCL2 is overexpressed in cancer cells, it suppresses pro-apoptotic signals, allowing the cancer cell to survive in stressful situations." (PMID 36882428, 2023). "Peptides and small molecules that inhibit BCL-2 proteins have been developed and are able to rescue the ability of cancer cells to undergo apoptosis by releasing BH3-only proteins such as BIM and BMF." (PMID 37761989, 2023). "The B-cell lymphocyte/leukemia 2 gene (Bcl-2) is a potent inhibitor of apoptosis and thereby a promising protective agent against doxorubicin and other cancer-therapy-induced cardiotoxicity." (PMID 37759797, 2023). "The Bcl-2 protein is a promising therapeutic target for treating carcinoma disease because of its capacity to control the programmed cell death of mitochondria." (PMID 36677841, 2023). "Another study reported that, in invasive uterine cervix squamous carcinoma, AM and Bcl-2 were involved in promoting malignant progression and in selecting carcinoma cells resistant to apoptosis." (PMID 36980580, 2023). "It was recently reported that HOTAIRM1 elicited apoptosis as presented by increased Bax expression and decreased Bcl-2 expression in carcinomas." (PMID 37529170, 2023). "In contrast, the T3 isomers (α-, γ-, and γ-T3) predominantly activate proteins involved in apoptotic signaling, such as Bax, Bid, Caspase-3, Caspase-8, cytochrome c, and TRAIL, while suppressing the Bcl-2 ratio, which is reported in various cancers." (PMID 35889829, 2022). "The low expression levels of BCL2 were reported to inhibit cell migration and proliferation, indicating its important role during cancer cell migration." (PMID 36233156, 2022). "Bcl-2, an antiapoptotic protein that is overexpressed in many cancers, inhibits the intrinsic mitochondria-mediated cell death process by preventing mitochondrial membrane permeabilization, which causes proapoptotic chemical leakage." (PMID 36124089, 2022). "MAPK pathway inhibits the apoptotic pathway through the inactivation of Bcl-2-associated death promoter (BAD) and this allows the activation of Bcl-2 and the resistance of cancer cells to apoptosis." (PMID 35834029, 2022). "Mcl-1 was expressed differentially in all cells, especially in cancer cells, and its expression was downregulated during apoptosis in many cell types in contrast to the anti-apoptotic Bcl-2 and Bcl-XL proteins." (PMID 35632731, 2022).
cancer (continued). "The activation of JAK2 and the resulting dimerization of P-STAT3 regulate gene expressions, such as Bcl2, cyclinD, survivin, and XIAP, which causes cancer cell proliferation and resistance to anticancer drugs." (PMID 36500220, 2022). "These processes were then followed by a molecular docking study to evaluate the role of the identified major active metabolites towards cancer cell lines, where Bcl-2 target protein’s binding mechanism for the eight major identified compounds was studied." (PMID 36355526, 2022). "The fate of the cancer cells exposed to the chemotherapeutic agents and the commitment to death depends on BCL-2 and its interactions." (PMID 36358660, 2022). "A previous study reported the aberrant expression of Bcl-2 according to cancer cell type, revealing that Bcl-2 was downregulated in most cancers." (PMID 36182900, 2022). "It has anticancer effects, which enhanced Bax, Bak, and PUMA and reduced Bcl-xL and Bcl-2 that activate caspases-9, inducing apoptosis in cancers." (PMID 35402265, 2022). "Any imbalance can cause disorders, with upregulation of the cell-guarding antiapoptotic Bcl-2 protein itself being common in many, often incurable, cancers." (PMID 36325615, 2022). "The ratio of BCL-2 to BAX is a factor that determines the relative sensitivity or resistance of cancer cells to apoptotic impulses and therapeutic drugs." (PMID 35328794, 2022). "MSNs decorated with G2-polyamidoamine (PAMAM) simultaneously load DOX and Bcl-2 siRNA to address multidrug-resistant cancer cells." (PMID 36005484, 2022). "This also explains why the prognostic significance of BCL2 expression depends on the type of cancer." (PMID 35814404, 2022). "Bcl-2 and cFLIP play pivotal roles in the cancer resistance and reduction of Bcl-2 and cFLIP participate in enhancing drug sensitivity." (PMID 35892954, 2022). "Bcl-2 plays an important role in supporting cell survival or establishing drug resistance in cancer cells." (PMID 35210368, 2022). "Cytoplasmic nucleolin binds to mRNAs of Bcl-2 and Bcl-xL to stabilize them, thereby protecting cancers against apoptosis." (PMID 36359210, 2022). "According to research findings, the balance of pro-apoptotic and anti-apoptotic proteins, including the BAX and BCL2, is effective in cancer cell growth." (PMID 35463725, 2022). "Studies have indicated a direct relationship between the cancer progression and the expression of anti-apoptotic genes of the Bcl-2 family, Also over expression of Bcl2 can lead to cancer resistance in a wide range of cancers." (PMID 35725497, 2022). "To discern the expression of BCL-2 in various cancer types, we examined the mRNA expression levels of BCL-2 from a large dataset of 30 cancer types pertaining to 1303 cell lines collected from the Cancer Cell Line Encyclopedia (CCLE) database." (PMID 36358660, 2022). "We further investigated the alteration of anti-apoptotic proteins, including Bcl-2 and cFLIP, which play a role in controlling the survival of the cancer cells." (PMID 35892954, 2022). "BCL2 is an anti-apoptotic protein expressed in high quantities in cancer cells that inhibits the intrinsic pathway of apoptosis." (PMID 36454941, 2022). "One of the many strategies that cancer cells evade death is through up-regulation of the BCL-2 anti-apoptotic proteins." (PMID 35201512, 2022). "Bcl-2 is a central protagonist in a wide range of human cancers, promoting cell survival, angiogenesis and chemotherapy resistance; this has prompted the development of Bcl-2-targeting drugs." (PMID 35056993, 2022). "A BH3 mimetic ABT-737 was shown to bind Bcl-2 and Bcl-xL with high affinity killing primary cancer cells." (PMID 36539401, 2022).
cancer (continued). "Identified as an oncoprotein in the mid-1980s and as a mediator of chemotherapy resistance in the mid-1990s, Bcl-2 has high potential as a cancer therapeutic target." (PMID 35056993, 2022). "In cancer therapy, P. grandiflorus induced apoptosis by reducing Bcl-2 expression, increasing Bax expression, and activating caspase and mitochondrial cytochrome c release in SKOV-3 human ovarian cancer cells." (PMID 35309872, 2022). "Targeting the BH4 domain with small molecules would be ideal in intervening in the BCL-2 anti-apoptotic function in various resistant cancers." (PMID 36358660, 2022). "Studies have shown that mutations in the BCL-2 and BAX proteins are frequently detected in several types of cancers, suggesting that they play crucial roles in elucidating molecular mechanisms driving oncogenic transformation and drug resistance." (PMID 36313628, 2022). "MIR503HG knockdown remarkably upregulated Bax, Bad, cleaved caspase-3 and cleaved caspase-9 but downregulated Bcl-2 and survivin to promote apoptosis in cancer cells, thus suppressing NSCLC development." (PMID 35379783, 2022). "Some other BH3 mimetics are shown to disrupt the interaction between Beclin 1:Bcl-2 and induce autophagy of various cancer cells, namely gossypol, obatoclax, and ABT-737." (PMID 36309485, 2022). "Bcl-2, a proto-oncogene located on chromosome 18a21, inhibits cancer cell apoptosis, whereas Bax is a pro-apoptotic gene located on chromosome 19q13." (PMID 36309912, 2022). "In cancer, pro-apoptotic factors such as Bax are suppressed, and anti-apoptotic proteins, such as Bcl-2, are upregulated, promoting uncontrolled cell division." (PMID 35879795, 2022). "The induction of BCL2 modifier expression can induce mitochondria-dependent apoptosis in cancer cells." (PMID 36249029, 2022). "Thereby, AT-101 appears to target cancer stem cells by abrogating YAP1/SOX9/β-catenin signaling in addition to suppress anti-apoptotic signaling even when Bcl-2 is downregulated." (PMID 35215257, 2022). "EGCG has displayed the induction of apoptosis by enhancing caspase-3, caspase-9, BAD, cyt-c, PTEN, SMAC, and Fas and repressed Bcl-2, Bcl-xL, and c-Myc in cancer cells." (PMID 35402265, 2022). "Cancer cells commonly evade apoptosis through upregulation of the BCL-2 anti-apoptotic proteins; however, more resistant cancers also downregulate or inactivate pro-apoptotic proteins to suppress apoptosis." (PMID 35256598, 2022). "Bcl-2 inhibition is expected to trigger apoptosis in cancer cells because of its central role in the intrinsic apoptosis pathway." (PMID 36309485, 2022). "In these cancer types, miR‐204‐5p enhances apoptosis and reverses chemoresistance by inhibiting BCL2 expression." (PMID 35908280, 2022). "BAU-243 effectively reduced overall GBM cell proliferation including a subpopulation of cancer-initiating cells in contrast to the selective Bcl-2 inhibitor ABT-199." (PMID 36309485, 2022). "ITZ was reported to induce cancer cell death via apoptosis mainly due to alteration of mitochondria membrane potential, reduction of Bcl-2 expression and increase of caspase-3 activity." (PMID 35890264, 2022). "QC lowers the representation of anti-apoptotic proteins such as Bcl-xL, survivin, and Bcl-2, while improving the representation of pro-apoptotic proteins such as Bad and Bax to promote apoptosis in cancer cells." (PMID 35408561, 2022). "The Bcl-2 and Bcl-XL oncoproteins, which are overexpressed in many cancers, are thought to mediate oncogenesis by suppressing mitochondrial membrane permeabilization, one of the rate-limiting steps of apoptosis." (PMID 35456001, 2022). "Statistically, Bcl-2 antiapoptotic proteins showed abnormal expression in various malignancy, including 70% of breast cancers, 80% of B-cell lymphomas and other forms of cancer." (PMID 35414025, 2022).